SMIM3 (small integral membrane protein 3)
Synonyms: C5orf62; NID67; MSTP150; MST150
Tractability: Antibody: UniProt predicts a signal peptide or a membrane-spanning region.
Gene: Protein-coding gene on chromosome 5 (150,778,741 to 150,796,736, forward strand). Ensembl gene ENSG00000256235.
Subcellular location: Membrane
Subcellular location (Human Protein Atlas): Vesicles
Gene Ontology:
Molecular function: identical protein binding; protein binding
Cellular component: membrane
Genetic constraint (gnomAD): Loss-of-function variants: 4 observed, 2.26 expected, observed/expected ratio (o/e) 1.77, 90% interval 0.71 to 1.95. That is too few expected variants to judge how well the gene tolerates losing a copy. Missense variants: 79 observed, 79.55 expected, observed/expected ratio (o/e) 0.99, 90% interval 0.83 to 1.2. Synonymous variants: 29 observed, 31.52 expected, observed/expected ratio (o/e) 0.92, 90% interval 0.68 to 1.25.
Homologues: Orthologues: chimpanzee SMIM3 (100% identical), guinea pig SMIM3 (88% identical), pig SMIM3 (88% identical), rat Smim3 (83% identical), mouse Smim3 (82% identical).
Diseases named in the same sentence as SMIM3 in open-access papers:
SMIM3 is named in the same sentence as 10 diseases in open-access papers, as found by Europe PMC text mining. Sharing a sentence is not in itself a finding about the gene and the disease. The quoted sentences say what the papers report.
leukemia (2 papers, 2022 to 2024). A malignant (clonal) hematologic disorder, involving hematopoietic stem cells and characterized by the presence of primitive or atypical myeloid or lymphoid cells in the bone marrow and the blood. "On the other hand, for UNB, specific upregulated DEGs included SMIM3, a leukemia promoter gene, WNT7A, a hypoxia induced EMT driver, PADI2, a tumorigenic breast cancer gene, and RAPGEF4, which modulates gliomas." (PMID 38538643, 2024).
acute myeloid leukemia (1 paper, 2022). Acute myeloid leukemia (AML) is a group of neoplasms arising from precursor cells committed to the myeloid cell-line differentiation. "RT-qPCR suggested that SMIM3 was over-expressed in acute myeloid leukemia cell lines, while expressed with low level in lymphoma and myeloma cell lines." (PMID 36550462, 2022).
oral squamous cell carcinoma (1 paper, 2022). "A study revealed that SMIM3 may be associated with poor prognosis in oral squamous cell carcinoma, which needs to be further verified." (PMID 36550462, 2022). "However, more evidence is needed to prove whether SMIM3 is a prognostic biomarker in oral squamous cell carcinoma." (PMID 36550462, 2022).
pheochromocytoma (1 paper, 2022). "Current studies found multiple connections between SMIM3 and various diseases, including pheochromocytoma, 5q- syndrome of MDS and radiation exposure." (PMID 36550462, 2022).
tumor (2 papers, 2020 to 2022). "The tumor formation in nude mice revealed that the volume and weight of tumor in the experimental group with SMIM3 knockdown were significantly reduced than that of the control group." (PMID 36550462, 2022). "Our study showed that in Kasumi-1and THP-1 cells, the knockdown of SMIM3 significantly suppressed tumor growth compared to that in the control group." (PMID 36550462, 2022). "This suggests that SMIM3 has complex regulatory roles, and can act as either a potential oncogene or a tumor suppressor gene in different cancer types." (PMID 36550462, 2022). "The result of Ki67 and HE staining confirmed that the knockdown of SMIM3 inhibited tumor growth." (PMID 36550462, 2022). "The reduced SMIM3 expression significantly suppressed tumor growth in the xenograft mouse model." (PMID 36550462, 2022). "The biological functions of SMIM3 in vivo were validated by xenograft tumor mouse model." (PMID 36550462, 2022).
cancer (1 paper, 2022). A tumor composed of atypical neoplastic, often pleomorphic cells that invade other tissues. "We performed a pan‐cancer expression analysis of SMIM3 and showed that SMIM3 was highly upregulated in 8 cancers and commonly downregulated in 16 cancers." (PMID 36550462, 2022). "There are few studies on the biological functions of SMIM3 in different cancers." (PMID 36550462, 2022). "We compared the expression of SMIM3 in GTEX database, UCSC XENA and TCGA database, and results showed that SMIM3 is significantly overexpressed in 8 cancers, including LAML, and reduced in 16 cancers." (PMID 36550462, 2022).
hematological disease (1 paper, 2022). "We then detected the transcriptional level of SMIM3 in cell lines of hematological malignancies." (PMID 36550462, 2022). "Currently, SMIM3-related hematological disease is 5q- syndrome of MDS." (PMID 36550462, 2022).
SMIM3 also shares sentences with these, for which no sentence is quoted: breast carcinoma (1 paper); lymphoma (1); myeloma (1).